IRF1 (interferon regulatory factor 1)
Diseases named in the same sentence as IRF1 in open-access papers (continued):
Sharing a sentence is not in itself a finding about the gene and the disease.
hepatocellular carcinoma (43 papers, 2007 to 2025). A malignant tumor that arises from hepatocytes. "Lastly, The pro-proliferative effect of METTL3 on hepatocellular carcinoma was mechanistically linked to IRF1/c-Src axis activation, as evidenced by our experimental data." (PMID 40612868, 2025). "For example, EZH2 methyltransferase activity in hepatocellular carcinoma cells caused H3K27me3 histone modification near IRF1 and CD274 promoter regions, which suppressed their expression without affecting the IFNγ/STAT1 signaling pathway." (PMID 38396830, 2024). "Taken together, the regulation of miR-301a on IRF-1 expression is implicated in the pathogenesis of hepatocellular carcinoma." (PMID 35572537, 2022). "The authors proposed that EZH2 suppresses PD-L1 expression via epigenetic modification, by upregulating H3K27me3 levels at the CD274 (which encodes PD-L1) and IRF1 gene in hepatoma cells, highlighting the critical role of EZH2 in reshaping the tumour immune microenvironment." (PMID 40310411, 2025). "Additionally, through the IFN-γ/p-STAT1/IRF1 pathway, Nur77 causes NK-cell dysfunction in hepatocellular carcinoma." (PMID 38789431, 2024). "Moreover, re-expression of IRF1 also partly rescued the reduced luciferase activity of P1 caused by knockdown of IRF1 in the EZH2-silenced hepatoma cells." (PMID 31727135, 2019). "Recently, it has also been reported that high IRF-1 expression in hepatocellular carcinoma (HCC) is associated with better outcome in terms of frequency of recurrence following surgical resection." (PMID 29599126, 2018). "Nr4a1 was noted to mediate NK cell dysfunction in hepatocellular carcinoma via the IFN-γ/p-STAT1/IRF1 pathway." (PMID 40083382, 2025). "Emerging evidence showed the role of IRF1 in liver diseases, including hepatic ischemia-reperfusion injury, concanavalin A–induced liver injury, liver fibrosis, and hepatocellular carcinoma." (PMID 40577472, 2025). "In the context of mouse tumor models, NR4A1 (Nuclear Receptor 4A1) has emerged as a significant player, mediating NK-cell dysfunction in hepatocellular carcinoma through the IFNγ/p-STAT1/IRF1 pathway." (PMID 39920136, 2025). "Our findings revealed that METTL3 upregulates SRC expression in hepatocellular carcinoma through IRF1-dependent regulation." (PMID 40612868, 2025). "The SAMD1 protein, which was upregulated in hepatocellular carcinoma cells, can also inhibit IRF1 transcription." (PMID 38396830, 2024). "Stimulation of hepatocellular carcinoma cells with IFNγ led to an increase in the amount of IRF1 and, subsequently, the amount of PD-L1 in the cells." (PMID 38396830, 2024). "Other studies have shown that Sp1, IRF1 and IRF2 can bind to the APOL1 promoter in hepatoma cells, and IRF1, IRF2 and STAT2 to the APOL1 promoter in podocytes and endothelial cells." (PMID 37924378, 2024). "In hepatocellular carcinoma cells, nuclear interleukin-33 (IL-33) SUMOylation stabilizes IRF1 to aid in immunological evasion." (PMID 38789431, 2024). "The relevant studies have reported that NLRP3 inflammasome upregulates the expression of PD-L1 in patients with diffuse large B-cell lymphoma, and IRF1 promoted the expression of PD-L1 in hepatoma cells." (PMID 37325556, 2023). "miRNA-23a is also seen to downregulate the expression of interferon regulatory factor-1 in hepatocellular carcinoma cells." (PMID 37925508, 2023). "Expression of miR-301a has been increased in primary hepatocellular carcinoma tumors and cell lines, parallel with down-regulation of IRF-1." (PMID 35572537, 2022). "This is consistent with the previously reported finding that IRF1 expression strongly induces RARRES3 expression in human hepatoma and skin fibroblast derived cell lines." (PMID 34871166, 2021). "The prognostic values of IRF-1 and Ki-67 for liver transplantation (LT) of hepatocellular carcinoma (HCC) were investigated, as well as the mechanisms of IRF-1 in tumor suppression." (PMID 27191889, 2016).
hepatocellular carcinoma (continued). "We analyzed the GEO dataset, GSE26817 that contains data from a study on IRF1 transduction in Huh-7 human hepatoma cells." (PMID 25893139, 2013). "However, in hepatocellular carcinoma cells, EZH2 enhances H3K27me3 at the promoters of CD274, which encodes PD-L1, and interferon regulatory factor 1 (IRF1), leading to an inverse correlation by inhibiting PD-L1 expression." (PMID 40308579, 2025). "In addition, IFN-γ was found to trigger ferroptosis in hepatocellular carcinoma by activating the STAT1/IRF1/ACSL4 axis." (PMID 40140647, 2025). "It is also noteworthy that HDAC inhibitors are known to limit the growth of cancer cells and trigger their apoptosis by virtue of inducing autophagy, while there is further evidence to suggest that IRF1 can inhibit the growth of hepatocellular carcinoma cells by inducing autophagy." (PMID 36035205, 2022). "Previously published literature has further confirmed that HDAC inhibitors can inhibit the malignant features of cancer cells by inducing autophagy; meanwhile, IRF1 is also known to suppress the growth of human hepatocellular carcinoma cells by inducing autophagy." (PMID 36035205, 2022). "Similarly, IL-27 has antiviral activity in hepatoma cells and can induce the expression of IRF-1, guanylate binding protein 2 and MxA proteins that are involved in the antiviral response." (PMID 20719000, 2010). "In addition, studies have shown that the overexpression of EZH2 can inhibit programmed cell death protein 1 (PD-L1) in prostate cancer and hepatocellular carcinoma by enhancing the H3K27me3 level of the interferon regulatory factor 1(IRF1) transcription factor." (PMID 36713412, 2022). "A recent study found that EZH2, in hepatoma cells, can suppress PD-L1 expression by directly upregulating H3K27me3 levels on the promoters of CD274, which encodes PD-L1 and interferon regulatory factor 1 (IRF1), an essential transcription factor for PD-L1 expression." (PMID 32708698, 2020). "The epigenetic modificator EZH2 can suppress the expression of immune checkpoint inhibitor PD-L1 by directly upregulating the promoter H3K27me3 levels of CD274 and IRF1 in hepatoma cells, and might serve as a potential therapeutic target for combination of immunotherapy for immune-activated HCC." (PMID 31727135, 2019). "Moreover, knockdown of IRF1 in EZH2-silenced hepatoma cells decreased the abundance of PD-L1." (PMID 31727135, 2019). "In hepatocellular carcinoma, inhibition of checkpoint kinase 1 (CHK1) increases IRF1 expression to induce apoptosis and trigger antitumor immunity through major histocompatibility complex (MHC) class I-associated chain A (MICA)." (PMID 38789431, 2024). "FGF21 promotes ferroptosis in hepatocellular carcinoma by upregulating Major vault protein (MVP), which enhances NOX4-mediated ROS production through IRF1 and YAP1 interactions." (PMID 39315094, 2024). "Up-regulation of IRF-1 or down-regulation of CHK1 induces cell apoptosis and increases PD-L1 expression in hepatocellular carcinoma cells." (PMID 35572537, 2022). "Another research investigating hepatocellular carcinoma (HCC) also found that IRF-1 was able to upregulate the IFN-γ-induced PDL1 mRNA and protein expressions, indicating a positive correlation between IRF1 and PDL1." (PMID 35664436, 2022). "After patients were treated with chemotherapy, the DNA of hepatoma cells was damaged, and interferon regulatory factor 1 (IRF1) was activated, stimulating M2 macrophages to secrete a large amount of MMP9 in the form of exosomes to hydrolyze MICA on the surface of hepatoma cells." (PMID 40563539, 2025). "Furthermore, both the intrinsic antitumor properties of IRF1 and its ability to influence the formation of the tumor immune microenvironment through the IRF1/CXCL10/CXCR3 axis were demonstrated in hepatocellular carcinoma." (PMID 38396830, 2024).
hepatocellular carcinoma (continued). "IRF-1 was significantly lower in hepatocellular carcinoma tumors than in noncancerous tissues, and activation of IRF-1 by IFN-γ-induced PD-L1 expression in vitro." (PMID 35092496, 2022). "Studies have previously found that miR-345 indirectly regulates the transcription factors Slug, Snail, and Twist by targeting interferon regulatory factor 1 (IRF1) to activate the mTOR/STAT3/Akt signaling pathway, which can slow down the EMT process of hepatoma." (PMID 35805066, 2022). "IRF1 was found to regulate C-X-C motif chemokine 10 (CXCL10)/chemokine receptor 3 (CXCR3) signaling axis, thereby further activating antitumor immunity in hepatocellular carcinoma (HCC)." (PMID 35664436, 2022). "IRF1, PSMB9, TAP1, ETV7, and PSMB10 were related to CD8+ T cell infiltration proportion in thyroid carcinoma, breast invasive carcinoma, head and neck squamous cell carcinoma, hepatocellular carcinoma, lung adenocarcinoma, and skin cutaneous melanoma." (PMID 33330025, 2020). "IRF1 is a critical transcriptional regulatory factor thatmodulates interferon stimulated gene (ISG) expression and has been shown to regulateHCV subgenomic replicon activity in cultured hepatoma cells." (PMID 21359205, 2011). "Interestingly, after treatment of human hepatoma cells with a combination of IFN-α and IFN-γ, transcriptional induction of selective ISGs (including xaf1) was found to be dependent upon IRF-1." (PMID 17376236, 2007). "For instance, IRF1 and IRF2 could de-activate PD-L1 expression in hepatocellular carcinoma." (PMID 38833018, 2024).
lung cancer (40 papers, 2013 to 2025). A malignant neoplasm involving the lung. "The expression of interferon regulatory factor 1 (IRF1) was downregulated by the activation of EGFR signaling in EGFR-mutated non–small cell lung cancer." (PMID 35847084, 2022). "Defects in IRF1 are associated with gastric and lung cancer, and myelogenous leukemia." (PMID 34202278, 2021). "Myricetin was found to directly bind to Jak1 and has been reported to prevent the phosphorylation of STAT1 and inhibit both the expression and nuclear translocation of IRF1 to suppress IFN-γ-induced IDO1 expression in human lung cancer cells." (PMID 40002369, 2025). "The overexpression of IRF1 significantly inhibit the proliferation, invasion and migration of A549 lung cancer cells; and IL-2 augment the function of IRF1 on A549 lung cancer cells." (PMID 38915471, 2024). "After 4 weeks of inoculation, we found that overexpression of IRF1 significantly inhibits the tumor growth of A549 lung cancer cells." (PMID 38915471, 2024). "IRF1 activation induces lung cancer cell death and suppresses KPNA2 expression to inhibit LUAD growth." (PMID 39384770, 2024). "EV miR-21 from hypoxic lung cancer cells promotes M2 polarization of macrophages and accelerates lung cancer development via IRF1." (PMID 39165926, 2024). "As showed the highest levels of IRF1 transcription and expression following cisplatin treatment, A549 lung cancer cells were chosen for further in vitro study." (PMID 38915471, 2024). "siRNA knockdown of interferon regulatory factor‐1 (IRF‐1) is responsible for the IFN‐gamma‐mediated PD‐L1 upregulation in human lung cancer cell lines." (PMID 36515567, 2023). "Under hypoxia, lung cancer cell exosomal miR-21 restricts IRF1 expression, which stimulates M2 macrophage polarization and ultimately contributes to lung cancer cell proliferation." (PMID 36979471, 2023). "In conclusion, hypoxic lung cancer cell-derived exosomal miR-21 promoted macrophage M2 polarization and induced lung cancer progression through targeting IRF1." (PMID 35897096, 2022). "In this study, we found that overexpression of IRF-1 promoted apoptotic cell death and induced mitochondrial depolarization and oxidative stress in A549 lung cancer cells." (PMID 35092496, 2022). "Compared to the levels in normal tissues, IRF-1 expression was significantly lower in lung cancer tissues and was a prognostic factor for NSCLC." (PMID 35092496, 2022). "In the current study, we first explored the expression of IRF-1 in lung cancer tissues using public databases and clinical samples." (PMID 35092496, 2022). "In human lung cancer cells, interferon regulatory factor 1 (IRF1) binds to the putative binding sequence in PD-L1 promoter region and induces the transcription depending on JAL/STAT pathway response to IFNγ." (PMID 35402280, 2022). "High miR-21 level in hypoxic environments promoted macrophage M2 polarization and induced lung cancer progression through targeting IRF1." (PMID 35897096, 2022). "Cisplatin-induced IRF-1 activation was assessed in different lung cancer cell lines by Western blotting." (PMID 35092496, 2022). "Analysis of the HPA database further verified the low IRF-1 protein levels in LUAD and LUSC, and the results indicated that IRF-1 protein levels were decreased in lung cancer tissues and lymph nodes compared to the levels in normal lymph nodes." (PMID 35092496, 2022). "Next, we observed cisplatin-induced IRF-1 activation and explored its effects on mitochondrial homeostasis, autophagy, and apoptosis in lung cancer cells." (PMID 35092496, 2022). "The detailed analysis of IRF1 target genes in lung cancer cells will be the subject of another, more extended study." (PMID 34681730, 2021). "We selected seven genes [4 unique genes (E2F6, TFDP1, SUV39H1, and HNRPD) for NSCLC and 3 genes (RBL1, IRF1, and HMGA1) for general events] for validation as diagnostic markers in lung cancer." (PMID 24564251, 2013).
lung cancer (continued). "Due to SP140’s ability to enhance STAT1/IRF1 signaling and increase PD-L1 expression in tumor-associated macrophages, it has emerged as a crucial biomarker of immune evasion and predictor of immunotherapy resistance in cancers such as HNSCC and lung cancer." (PMID 41188771, 2025). "And IL-2 injection enhanced the function of IRF1 on A549 lung cancer cells." (PMID 38915471, 2024). "Therefore, IRF1 and STAT1 were knockdown in lung cancer A549 cells, which decreased 20 ng/mL of IFNα/γ-mediated gene expression, including IRF1, STAT1, PD-L1, CXCL10, and ISG15." (PMID 38953994, 2024). "It is suggested that the synergistic effect of IRF1 and IL-2 in A549 lung cancer cells in vitro." (PMID 38915471, 2024). "In addition, western blot analysis of IRF-1 in clinical lung cancer tissues showed that IRF-1 expression was significantly downregulated in cancer tissues compared to the levels in normal tissues." (PMID 35092496, 2022). "Our study is helpful in understanding the mechanisms by which cisplatin kills lung cancer cells and provides further compelling evidence that IRF-1 is involved in the anti-cancer effect of cisplatin by promoting apoptosis and inhibiting autophagy to disturb mitochondrial homeostasis." (PMID 35092496, 2022). "IRF1 expression correlation with PD-L1 and PD-L2 also goes beyond lung cancer." (PMID 31159869, 2019). "IRF1 is downregulated in lung cancer, IPF and PAH datasets, probably because it represses the expression of genes involved in anti-proliferative response, such as BIRC5/survivin, CCNB1, CCNE1, CDK1, CDK2 and CDK4 and in immune response, such as FOXP3, IL4, ANXA2 and TLR4." (PMID 31867044, 2019). "Stabilized FRA1 negatively regulates interferon regulatory factor 1 (IRF1), which is required for the induction of RIG-I-like receptor (RLR)-encoding genes, and thereby negatively regulates the RIG-I-MAVS-IRF3 signaling axis in lung cancer cells and suppresses caspase 8-driven apoptosis." (PMID 40128585, 2025). "Moreover, PD-L1 expression is highly correlated with IRF1 in lung cancer." (PMID 34088360, 2021). "IRF1 and IL2 have a synergistic impact that inhibits the proliferation, migration, and invasion of A549 lung cancer cells, as demonstrated by both in vitro and in vivo tests." (PMID 38915471, 2024). "The results indicated that IFNα/γ-downstream IRF1 and STAT1 both potentially mediated PD-L1 and CXCL10 expression in lung cancer." (PMID 38953994, 2024). "A study reported that the blockade of EGFR by afatinib resulted in decreased STAT1 and IRF-1 levels, and disabled the IFN-γ-STAT1-mediated PD-L1 axis in vitro and in vivo for oral cancer and lung cancer." (PMID 37759950, 2023). "A comprehensive, in-depth understanding of the activity and mechanism of IRF-1 in NSCLC is of theoretical and practical significance for the treatment of lung cancer." (PMID 35092496, 2022). "Cisplatin treatment-induced IRF-1 activation, ROS production, ATP depletion, SOD consumption, and MDA accumulation in A549 lung cancer cells." (PMID 35092496, 2022). "Interferon regulatory factor-1 (IRF-1), a transcription factor, regulates the constitutive and IFN-γ-mediated PD-L1 expression in human lung cancer cell." (PMID 35069587, 2021). "The protein levels of PDL1, IRF1, IRF7, STAT1, STAT2, IFNAR1, eIF2α, and ATF4 in the normal and tumor tissues of 27 subjects with lung cancer were determined by Western blot." (PMID 30305853, 2018). "In our study, we observed IRF1 (Interferon regulatory factor 1) was upregulated in all NSCLC samples tested, although it had been shown to be downregulated in lung cancer in a previous study." (PMID 24564251, 2013).
lung cancer (continued). "Additionally, natural compounds like baicalin, solasodine, and ginsenoside Rh2 can also regulate ferroptosis in lung cancer cells by targeting key factors such as Nrf2, ATF4, HSP90, and IRF1." (PMID 41242017, 2025). "In conclusion, IRF1 and IRF3 present inhibitory functions in lung cancer." (PMID 39384770, 2024). "The endogenous interaction between IRF1 and ATXN3 was further confirmed in human lung cancer A549 cells, indicating that ATXN3 may enhance IFN-γ–induced PD-L1 expression through IRF1." (PMID 38038129, 2023). "We found that high levels of the 5 genes, PD-L1, ICAM-1, CXCL10, IRF1, and TAP1, were correlated with better survival probabilities in lung cancer patients treated with immunotherapies (N = 21, p = 0.17 for PD-L1, p = 0.28 for ICAM-1, p = 0.052 for CXCL10, p = 0.023 for IRF1, and p = 0.22 for TAP1)." (PMID 36688994, 2023). "Notably, ectotrophic expression of both IRF1 and STAT3 largely restored IFN-γ–induced PD-L1 expression in ATXN3-null lung cancer cells." (PMID 38038129, 2023). "Nevertheless, the activation status and function of IRF-1 in lung cancer and cisplatin resistance have not been reported." (PMID 35092496, 2022). "The significant correlations among eIF2α, ATF4, IRF1, and PDL1 in lung cancer may result from ER stress-induced UPR/ISR and the PD1/PDL1 reverse signaling." (PMID 30305853, 2018). "IRF1 is a tumor suppressor modulated by miR-23, promoting TGF-beta-induced EMT in lung cancer." (PMID 26187636, 2015). "Interestingly, knockdown of IRF1 alone did not significantly impact persistence with PRMT1 knockdown in three tested STAT-high lung cancer cell lines." (PMID 39699269, 2025). "The different correlation profiles of IRF1, eIF2α, ATF4, and PDL1 protein expressions in the normal and tumor tissues of lung cancer, especially adenocarcinoma, may be helpful in selecting conditions for combining ICI and inhibitors against IDO1 or modulators of ER stress." (PMID 30305853, 2018). "Cisplatin-induced IRF-1 activation differently in the tested cell lines; cisplatin-induced IRF-1 activation only in A549, SK-MES-1, and H460 cells, but not in the other tested lung cancer cells." (PMID 35092496, 2022).